VHL (von Hippel-Lindau tumor suppressor)
Diseases named in the same sentence as VHL in open-access papers (continued):
Sharing a sentence is not in itself a finding about the gene and the disease.
tumor (continued). "Two HIF transcription factors comprise the best characterized elements of this response: both are oxygen sensitive and in both cases their activity can be regulated post-transcriptionally, via the von Hippel-Lindau (VHL) tumor-suppressor complex and the FIH asparagine hydroxylase." (PMID 29136509, 2017). "Unilateral or bilateral amaurosis is relatively frequent among the VHL population due to the development of multiple tumours, which in many cases could be prevented or delayed with proper monitoring and early treatment." (PMID 28662711, 2017). "Finally, it is important to mention that at least in tumor cells a functional VHL pathway is involved in assembly and remodeling of the ECM (e.g collagen IV and fibronectin) in a HIF-independent manner." (PMID 28118605, 2017). "VHL gene is a tumor suppressor gene, located on the short arm of chromosome 3." (PMID 28785532, 2017). "However, both forms are associated with gene mutations to the short arm of chromosome 3 and specifically to the VHL tumor suppressor gene." (PMID 28153029, 2017). "In VHL-deficient tumor cells and endothelial cells, HIF2α rather than HIF1α is the main positive regulator of tumorigenesis and angiogenesis." (PMID 28247252, 2017). "Both isoforms are important for tumor suppressor effects of the VHL gene." (PMID 28785532, 2017). "The VHL gene is a tumor suppressor gene located on the short-arm of chromosome 3 (3p25)." (PMID 27819754, 2017). "We next examined whether human ccRCC tumours with similar genomic characteristics (VHL inactivation; VHL inactivation and MYC activation; and VHL inactivation, CDKN2A loss and MYC activation) have similar outcomes as those seen in our mouse models." (PMID 28593993, 2017). "Somatic VHL mutations (i.e. mutations in tumor but not germline DNA) have been also described in about 9% of PGLs." (PMID 28036268, 2017). "VHL inactivation is considered as a critical part of tumor initiation." (PMID 28052007, 2017). "Considering the fact that tumor risks for VHL patients may be influenced by sex, family history and mutation types, we performed univariate and multivariate Cox regression analyses to evaluate age‐related tumor risks in VHL patients." (PMID 28776935, 2017). "Importantly, tumors with identical pathology can also be related to VHL, RET1 and NF1 mutations, indicating a similar pathogenesis for tumor formation." (PMID 28911113, 2017). "We posit that this is a general pattern of hereditary cancer predisposition, wherein haploinsufficiency for VHL or TSC1/2, or potentially other tumor susceptibility genes, is sufficient to promote development of early lesions, while cancer results from inactivation of the remaining normal allele." (PMID 27682873, 2017). "Under aerobic conditions, proline residues (Pro402 and Pro564) located in the oxygen-dependent degradation domain of HIF-1α are hydroxylated by PHD2, which results in recognition of the subunit by the VHL protein (von Hippel-Lindau tumour suppressor), a part of the ubiquitin ligase complex E3." (PMID 27326424, 2017). "In this study, we found knockdown of SENP1 inhibits the proliferation of RCC4/VHL cells under hypoxic conditions, and SENP1 expression is positively associated with tumor grade in ccRCC, suggesting it as a potential biomarker for tumor differentiation and aggressiveness." (PMID 27741516, 2016). "The VHL gene is located on the short arm of chromosome 3 (3p) and is a tumor suppressor gene." (PMID 27446927, 2016). "The tumor-suppressive function of VHL gene depends on its promoting effect on miR-204 expression." (PMID 27438705, 2016). "This cell line recapitulates the VHL mutation and somatic copy number alteration profile of the patient’s primary tumour (data not shown)." (PMID 27121191, 2016).
tumor (continued). "Our finding suggested that the miR-101/VHL/HIF1α axis may play a tumor suppressive role when adequate oxygen was supplied to the tumor." (PMID 26841847, 2016). "Pro-angiogenic VHL null granulocytes/neutrophils could therefore contribute to the development of the tumor vasculature." (PMID 27733136, 2016). "VHL is a tumour suppressor gene inactivated in clear cell renal cell carcinoma (ccRCC)." (PMID 27174753, 2016). "The goal of our study was therefore to sequence the VHL tumor suppressor gene in 360 ccRCC patients and characterize missense mutations by focusing on preferentially affected sites in the gene and their potential consequences on pVHL function and its binding partners." (PMID 27530247, 2016). "It is therefore possible that in VHL patients, VHL inactivation could also occur in the tumor microenvironment (stroma) in addition to the tumor itself." (PMID 27733136, 2016). "VHL was a 213 amino acid protein product of the VHL tumor suppressor gene." (PMID 27222660, 2016). "Therefore, the upregulation of p62 in some types of tumor probably results in dissociation of HIFα from the VHL E3 ligase complex and the formation of a heterodimer with HIFβ, followed by transcriptional activation of HIF target genes." (PMID 26743088, 2016). "Mutations in crucial genes, including VHL and PTEN, were present in only one tumor in each patient." (PMID 27383411, 2016). "In patient BC_4, a frameshift insertion in exon 1 was present in the left tumor, while no VHL mutation was detected in two different regions of the right tumor examined." (PMID 27383411, 2016). "Clear cell RCCs generally carry genetic abnormalities of the VHL tumor suppresser genes." (PMID 27157976, 2016). "Here, the authors sequence multiple renal tumours from VHL patients and find that intra-patient tumours are clonally distinct but share some genetic features, suggesting that patient-specific factors influence tumour formation." (PMID 27174753, 2016). "Histone demethylase activity of KDM5C was required in the function of VHL in tumor growth." (PMID 26848523, 2016). "We speculated that, in some instances, the decreased C12orf59 expression and the loss of VHL might cooperate to promote the development of ccRCC because VHL inactivation alone is insufficient for tumor initiation." (PMID 26758419, 2016). "Treatment of VHL is complex due to the multisystem involvement, the location of tumors, and the immense variability of symptoms that can be produced related to various tumor locations and systems involved." (PMID 27446927, 2016). "In these two cases, two tumors within the same patient did not harber the same founder driver mutations, 3p LOH and VHL mutation/hypermethylation, indicating their independent tumor origin." (PMID 27383411, 2016). "These four tumor suppressor genes may act alone or cooperate with VHL inactivation to initiate tumor formation and/or promote progression." (PMID 25714014, 2015). "Thus NF1, VHL, RET, and MAX germline and somatic mutations have been reported in 3–25%, 13–9%, 5–5%, and 1–3% of tumours, respectively." (PMID 25883647, 2015). "Thus, in kidney cells, miR-204, in a network involving VHL, functions as a tumor suppressor miR that inhibits pro-oncogenic autophagy by targeting LC3B mRNA." (PMID 28326269, 2015). "Hence, a drug targeting HIF, and thus the genes it regulates, would be the ideal strategy to delay VHL tumor progression." (PMID 26394686, 2015). "As secreted proteins are supposed to be involved in the interaction amongst these cells within the tumor microenvironment the VHL-regulated cross talk between tumor cells and T lymphocytes and the involvement of the secretome in this process was analyzed in the present study." (PMID 26486078, 2015). "An exciting proposition to consider is whether upregulation of VHL by GA promotes these additional HIF-independent mechanisms to block tumor growth and development." (PMID 28326255, 2015).
tumor (continued). "It has been observed that the VHL loss of function is not sufficient to explain tumor formation in kidney." (PMID 26579493, 2015). "Although the most frequently altered gene in this locus is von-Hippel Lindau tumor suppressor (VHL), there does not appear to be any association with mutation status to tumor aggressiveness and clinical outcome, making VHL a poor prognostic biomarker." (PMID 25124064, 2014). "Loss of heterozygosity (LOH) was observed in 1/1 SDHB, 11/11 VHL and 3/3 NF1-associated tumours." (PMID 24466223, 2014). "Again, the known VHL/HIF pathway related gene sets were upregulated in tumor samples." (PMID 24783204, 2014). "VHL exerts its tumor-suppressive activity by inducing degradation of HIFα proteins, but it might also exert HIF-independent activities." (PMID 24657971, 2014). "All tumor regions also displayed 3p LOH, which we have previously found to be the only common early event in sporadic clear cell renal tumorigenesis together with VHL mutation or methylation." (PMID 25159823, 2014). "A major step in the initiation of the RCC is the VHL tumor-suppressor gene inactivation." (PMID 24657971, 2014). "Von Hippel Lindau (VHL) is a tumor suppressor gene, located on chromosome 3." (PMID 25097537, 2014). "This is seen in tumours that do not have known VHL mutations, and this represents a novel mechanism of HIF-1α accumulation." (PMID 24563687, 2014). "In tumor cells, HIF-1α may also be regulated by other genetic factors, including oncogenes (Ras and PI3-K) or the loss of tumor suppressors [VHL or phosphatase and tensin homolog (PTEN)] even under aerobic conditions." (PMID 23833638, 2013). "Recently, we discovered that another tumor-suppressing pathway is regulated by VHL." (PMID 23922894, 2013). "It is well established that loss of VHL results in increased accumulation and activity of the hypoxia-inducible transcription factor (HIF), which in turns activates expression of genes that promote tumor growth." (PMID 23922894, 2013). "It is an open question whether the overexpression of a single HRG is capable of driving efficient tumor growth in VHL+/+ 786-O cells as HIF2α could." (PMID 24260413, 2013). "However, these cells grew into much smaller tumors than the cells expressing SCR, which strongly suggests that Cyclin D1, like VEGF, also promoted tumor growth by the VHL-/- cancer cells in mice." (PMID 24260413, 2013). "The overexpression of neither VEGF nor CCND1 in VHL+/+ 786-O cells was able to cause robust tumor growth (data not shown)." (PMID 24260413, 2013). "Despite the observation that the reintroduction of wild type VHL in a VHL-null ccRCC cell line inhibits tumorigenesis, the molecular basis of tumour formation and progression upon VHL inactivation remains unclear." (PMID 23785518, 2013). "Key molecular events in the pathogenesis of RCC include inactivation of the VHL tumour suppressor gene (TSG), inactivation of chromosome 3p TSGs implicated in chromatin modification and remodelling and de novo tumour-specific promoter methylation of renal TSGs." (PMID 24034811, 2013). "Loss of VHL results in the upregulation of VEGF production and induction of tumor angiogenesis." (PMID 22965141, 2012). "A third, small (14%) cluster of tumours could also be identified, 82% of which were classed as VHL wild-type." (PMID 23016578, 2012). "Tumour hypoxia, independent of VHL loss of function, increases EGFR expression through early growth response factor 1 (Egr-1)." (PMID 22937740, 2012). "Thus, we evaluated levels of malondialdehyde as an index of lipid peroxidation, and dihydroethidium (DHE) fluorescence for SDHB- and VHL-derived tumor tissues." (PMID 22859959, 2012).
tumor (continued). "Our previous study has demonstrated that TGFBI-promoted metastasis of RCC cells depends on inactivation of the von Hippel-Lindau (VHL) tumor suppressor and that TGFBI could be a therapeutic target against RCC in the future." (PMID 22950635, 2012). "More than 90% of sporadic ccRCCs have VHL involvement, almost defining this subgroup of tumours." (PMID 23016578, 2012). "Loss-of-function mutations in the remaining VHL allele are thought to represent an early event in ccRCC development but are not sufficient alone to drive tumour growth." (PMID 23016578, 2012). "With regard to tumor suppressors, the best characterized example is the role of VHL in CAIX upregulation wherein mutation of VHL results in constitutive stabilization of HIF-1 in normoxia and drives hypoxia-independent expression of HIF-1 regulated genes, including CAIX." (PMID 22289741, 2012). "In the 28 tumours without VHL mutation in our previous study, mutations were identified in two using RNA." (PMID 22825683, 2012). "The answer appears to be that it is not as there was no second hit from somatic cell mutation of the wild type VHL allele, although there was loss of the mutant allele in the tumor tissue." (PMID 22462637, 2012). "Next, we performed immunohistochemistry to detect HIF-1α, CDCP1 and VHL protein in tumor tissue." (PMID 22390300, 2012). "Moreover, whereas CDCP1 and HIF-1α expression were reduced in KAI1-expressing tumor tissue, VHL expression was clearly augmented." (PMID 22390300, 2012). "The suppressor gene of the VHL tumor consists of 3 exons and 639 NT (N-terminal)." (PMID 23843833, 2012). "Generally, the target gene VHL was transferred into tumor area by FA-PEAs to suppress tumor growth." (PMID 21513541, 2011). "The lack of an association between VHL alteration prevalence and indicators of tumor progression was similar to some previous reports." (PMID 22022277, 2011). "Lastly, VHL gene inactivation in RCC tumor tissue is frequently (up to 91%) observed." (PMID 22076155, 2011). "However, several lines of evidence suggest that there are unidentified substrates or targets for VHL that play important roles in tumor suppression." (PMID 21386990, 2011). "Sunitinib produced a more potent reduction of tumour burden in the 786-O cell line, which may be due to its VHL−/− status." (PMID 22015557, 2011). "That increased activity of HIF is associated with increased apoptosis may appear counter-intuitive, in view of the evidence that suppressing of HIF is a major aspect of VHL's action as a tumour suppressor in the kidney." (PMID 21386837, 2011). "The development of tumours in VHL disease results from loss or inactivation of the remaining wild-type allele, leading to an absence of functional VHL protein." (PMID 21673679, 2011). "Interestingly, associations were observed with several tag SNPs spanning the VHL gene in germline DNA and tumor-specific VHL promoter hypermethylation." (PMID 22022277, 2011). "Lastly, the prevalence of VHL gene epigenetic inactivation in tumor tissue was only about 9%." (PMID 22022277, 2011). "Von Hippel-Lindau (VHL) alteration leading to protein inactivation is considered a frequent, early event in renal carcinogenesis that can be used as a biomarker of tumor heterogeneity, to strengthen etiologic relationships with risk factors, and study mechanistic pathways of disease." (PMID 22022277, 2011). "In this report, we now showed that PIASy, a SUMO E3 ligase, is up-regulated by hypoxia and stimulates VHL SUMOylation on lysine residue 171, which facilitates VHL oligomerization and inactivates VHL as a tumor suppressor in both a HIFα-dependent and independent strategy." (PMID 20300531, 2010). "If later on, some key non-VHL TSG genes from 3p, 8p, and/or 14q undergo mutations or gene alterations, leading to the losses of the functions of the corresponding genes, the tumor cells then get sufficient potential toward tumorigenesis, finishing the first step of tumor formation in the sequence." (PMID 20671976, 2010).
tumor (continued). "Thus, SUMO modification of VHL is necessary for tumor cell growth in three-dimensional space mimicking the in vivo multicellular tumor growth conditions." (PMID 20300531, 2010). "To ascertain if SUMO modification is sufficient to inactivate the inhibitory functions of VHL on tumor cells, we tested whether PIASy-induced SUMO1 modification of VHL resulted in dysregulation of VHL as the cells exit the cell cycle on serum deprivation." (PMID 20300531, 2010). "Our data suggest that WP1066 suppresses VEGF production and tumour angiogenesis under both normoxic and hypoxic conditions regardless of the VHL gene mutation status." (PMID 20461084, 2010). "Moreover, PIASy-mediated SUMO1 modification induces VHL oligomerization and abrogates its inhibitory function on tumor cell growth, migration and clonogenicity." (PMID 20300531, 2010). "Although a great deal of effort has been put into studying the molecular mechanism of hypoxia stress on HIFα stabilization via posttranslational regulation, it still remains unclear whether hypoxia affects overall VHL tumor suppressor function." (PMID 20300531, 2010). "The von Hippel–Lindau (VHL) tumour suppressor has been isolated in 1993." (PMID 19755989, 2009). "The VHL tumor suppressor gene resides on chromosome 3p25 and consists of three exons." (PMID 19602254, 2009). "When selecting tumours with undetectable pVHL and at least one VHL alteration (n=67, 68.4%) and comparing this former group to tumours expressing pVHL (n=31, 31.6%), the first group exhibited better outcome both in terms of PFS (log-rank test, P=0.02) and in terms of RCC-SS (log-rank test P=0.03)." (PMID 19755989, 2009). "Thus, the SHH signaling pathway is constitutively expressed and activated in tumor cells and independently of VHL expression." (PMID 20015350, 2009). "Both VEGF tumour and plasma expression appeared to be decreased in case of VHL alteration." (PMID 19755989, 2009). "Although there was a trend for better PFS and RCC-SS in patients with VHL-mutated tumours, it did not achieve statistical significance (log-rank test, P=0.1 and 0.2, respectively)." (PMID 19755989, 2009). "Based on the data presented in this report and elsewhere, we speculate that the proper control of integrins and tight junctions may be important for VHL tumor suppressor function at the early stages of tumor formation." (PMID 19602254, 2009). "The role of VHL as a tumor suppressor is principally mediated via its interaction with HIFs." (PMID 19955664, 2009). "Meanwhile, a hypothesis has been deduced from cell culture studies, which proposes loss of an enzymatic function required for HIF1α-degradation as the key mediator of SDH dysfunction, thus, connecting this novel tumor suppressor with the classical VHL gene." (PMID 19949549, 2009). "Since the detection rate for VHL gene mutations is nearly 100%, molecular testingmay also be used to evaluate individuals with a single VHL-associated tumor anda negative family history of the disease." (PMID 19009041, 2008). "VHL is characterised by highly vascularised tumours in different organs." (PMID 17922902, 2007). "Fibronectin matrix assembly has been suggested to be a key VHL function for VHL tumor suppression." (PMID 17598890, 2007). "VHL is a tumour suppressor gene involved in the development of clear cell RCC." (PMID 17211469, 2007). "Thus, the VHL gene was entirely sequenced (ie 100% of the coding sequence analysed) for a total of 26 tumours (54%)." (PMID 17997830, 2007). "Given the important role of MT1-MMP in the progression of other cancers, we hypothesized that as a HIF-2α target, MT1-MMP may play a role in the progression of VHL-/- RCC tumor invasion to metastatic disease." (PMID 17140440, 2006). "In this study, we show that somatic VHL mutation and deletion are involved in tumor progression rather than tumor initiation of MEN 2A-related MTC." (PMID 16707008, 2006). "The VHL tumor suppressor is a key mediator of the hypoxia response." (PMID 16103922, 2005).